CLDN3 (claudin 3)
Diseases named in the same sentence as CLDN3 in open-access papers (continued):
Sharing a sentence is not in itself a finding about the gene and the disease.
Cirrhosis (5 papers, 2014 to 2024). A chronic disorder of the liver in which liver tissue becomes scarred and is partially replaced by regenerative nodules and fibrotic tissue resulting in loss of liver function. "In addition, blood levels of biomarkers of intestinal barrier damage (diamine oxidase [DAO], claudin 3, and others) are altered in cirrhosis and associated with bacterial translocation." (PMID 38543514, 2024). "The level of claudin 3 in the blood of patients with cirrhosis was directly correlated with the abundance of Anaerostipes and inversely correlated with the abundance of Brucella, Coriobacteriia, Eggerthellaceae, and Lactobacillus in the gut microbiota." (PMID 38543514, 2024). "Patients with cirrhosis had higher plasma levels of claudin 3, LPS, presepsin, and TNF-α, and lower plasma levels of DAO." (PMID 38543514, 2024). "The Eggerthellaceae genus is positively correlated with the total gastrointestinal symptoms (including constipation) in children with autism spectrum disorder and negatively correlated with the levels of Claudin 3 in patients with cirrhosis." (PMID 39734674, 2024). "Claudin 3 levels in cirrhosis have been examined in only one study previously." (PMID 38543514, 2024). "The level of claudin 3 in alcoholic cirrhosis was lower than in the combined group of cirrhosis of other and unknown origin (p = 0.007), without a significant difference between viral (p = 0.458), and mixed alcoholic and viral (p = 0.703) cirrhosis." (PMID 38543514, 2024). "Presepsin, claudin 3, nitrite, and ADMA levels were higher in patients with cirrhosis than in controls." (PMID 38396668, 2024). "Compared with patients with normal DAO levels, patients with decreased levels had higher levels of claudin 3, LPS, presepsin, TNF-a, and total bilirubin as well as more severe cirrhosis." (PMID 38543514, 2024). "The blood levels of DAO were inversely correlated with blood levels of claudin 3, lipopolysaccharide (LPS), presepsin, TNF-α, and the severity of cirrhosis according to Child–Pugh scores." (PMID 38543514, 2024). "The aim of this study was to examine the association of intestinal damage biomarkers (diamine oxidase [DAO], claudin 3, and intestinal fatty acid binding protein [I-FABP; FABP2]) with the state of the gut microbiota in cirrhosis." (PMID 38543514, 2024). "Presepsin, claudin 3, nitrite, and ADMA levels were higher in cirrhosis patients than in controls." (PMID 38396668, 2024). "Claudin 3 blood levels in patients with cirrhosis classes B and C were higher than those in patients with cirrhosis class A and healthy controls, but were not significantly different between classes B and C." (PMID 38543514, 2024). "Thus, we can divide the cirrhosis group into subgroups with normal and decreased DAO levels, normal and increased claudin 3 levels, and with detected and undetected I-FABP." (PMID 38543514, 2024). "The blood levels of DAO were significantly inversely correlated with blood levels of claudin 3 (r = −0.373; p = 0.002), LPS (r = −0.275; p = 0.027), presepsin (r = −0.310; p = 0.012), TNF-α (r = −0.310; p = 0.012), and the severity of cirrhosis according to Child–Pugh scores (r = −0.249; p = 0.045)." (PMID 38543514, 2024).
Crohn disease (5 papers, 2017 to 2025). A gastrointestinal disorder characterized by chronic inflammation involving all layers of the intestinal wall, noncaseating granulomas affecting the intestinal wall and regional lymph nodes, and transmural fibrosis. "In patients with Crohn’s disease, proteins such as Occludin, Claudin-3, -5, -8 are notably decreased and redistributed." (PMID 41031160, 2025). "In Crohn’s disease, upregulation of claudin-1 and claudin-2 and decreased expression of intestinal epithelial isoforms claudin-3, -5, -8, and -12 were reported." (PMID 39334888, 2024). "Clinical studies showed that, in patients with Crohn’s disease (CD), the expression of claudin-3 and occludin was decreased." (PMID 29280945, 2017).
endometriosis (5 papers, 2019 to 2023). The growth of functional endometrial tissue in anatomic sites outside the uterine body. "Studies have shown lower expression of claudin-3 and claudin-4 in ectopic endometriosis tissue compared to eutopic endometrium in women with endometriosis at messenger mRNA and protein levels." (PMID 37446108, 2023). "In the human endometrium with endometriosis, an impaired expression of claudin-3, -5 and -7 has previously been identified." (PMID 32140805, 2020). "Downregulation of claudin-3, claudin-4, and claudin-7 may contribute to the establishment of endometriosis." (PMID 36091010, 2022). "From our results, we conclude that localization of claudin-2 and claudin-3 is highly stable in eutopic and ectopic endometrium without any loss of the epithelial phenotype and thus do not contribute to the pathogenesis of endometriosis." (PMID 32140805, 2020). "Thus, in this study, we examined claudin-2 and claudin-3 expression in eutopic and ectopic endometrium to further clarify the role of cell-to-cell contacts in endometriosis." (PMID 32140805, 2020). "Positivity for claudin-3 was further identified in almost all ectopic endometriotic epithelial cells and lesions irrespective of the three endometriotic entities: ovarian, peritoneal or deep-infiltrating endometriosis." (PMID 32140805, 2020). "Thus, it remains unclear why in endometriosis, a downregulation of claudin-3 should contribute to the dissemination of endometrial cells." (PMID 32140805, 2020). "A detailed quantification with HSCORE was performed for claudin-2 and claudin-3 in endometrium without endometriosis and in cases with endometriosis compared to the three endometriotic entities: peritoneal, ovarian, and deep-infiltrating endometriosis." (PMID 32140805, 2020). "Localization of claudin-3 in patients with and without endometriosis was strong in the membranes of glandular eutopic epithelial cells, nearly approaching 100% of all epithelial cells in both the proliferative and the secretory phase." (PMID 32140805, 2020).
glioma (5 papers, 2017 to 2026). A benign or malignant brain and spinal cord tumor that arises from glial cells (astrocytes, oligodendrocytes, ependymal cells). "Downregulation of claudin-3 and claudin-5 expressions in high-grade glioma has been reported." (PMID 28978116, 2017). "Moreover, overexpression of CLDN3 support progression and metastasis of these malignancies, while reduced expression of CLDN1 and CLDN5 is observed in advanced gliomas." (PMID 41399659, 2026).
psoriasis (5 papers, 2020 to 2025). An autoimmune condition characterized by red, well-delineated plaques with silvery scales that are usually on the extensor surfaces and scalp. "Serum expression levels of Claudin-3 and I-FABP can serve as quantitative indicators of intestinal barrier integrity, with elevated levels predicting the risk of psoriasis recurrence." (PMID 41425939, 2025). "Patients with psoriasis typically exhibit increased intestinal permeability, with elevated serum levels of biomarkers such as Claudin-3, trimethylamine N-oxide (TMAO), and intestinal fatty acid binding protein (I-FABP), all of which are associated with compromised intestinal barrier function." (PMID 41425939, 2025). "They found that psoriasis patients had more elevated concentration of plasma claudin-3 and I-FABP, supporting the hypothesis that dysfunction of the intestinal barrier in psoriasis disturbs the homeostatic equilibrium between the microbiota and immune system." (PMID 33384669, 2020).
cholangiocarcinoma (4 papers, 2021 to 2025). A carcinoma that arises from the intrahepatic biliary tree (intrahepatic cholangiocarcinoma) or from the junction, or adjacent to the junction, of the right and left hepatic ducts (hilar cholangiocarcinoma). "Ten–eleven translocation protein 1 (TET1) exerts its pro‐carcinogenic effect in cholangiocarcinoma by catalyzing the demethylation of the claudin‐3 (CLDN3) promoter region." (PMID 39477806, 2024).
esophageal cancer (4 papers, 2014 to 2024). A primary or metastatic malignant neoplasm involving the esophagus. "Claudin-7 was reduced in LUAD, whereas claudin-3 and claudin-4 were increased in esophageal cancer." (PMID 38841188, 2024).
glioblastoma multiforme (4 papers, 2019 to 2026). "The selective loss of claudin-3 from TJs of the BBB in experimental autoimmune encephalomyelitis and human glioblastoma multiforme led to the conclusion that it might be a central component for the determination of the BBB’s integrity in vivo." (PMID 38203447, 2023). "Also, the selective loss of claudin-3 or occludin was observed in experimental allergic encephalomyelitis (EAE) and glioblastoma multiform (GBM) resulting in a loss in BBB integrity along with some functional barrier loss." (PMID 33208141, 2020). "Additional evidence for a role of claudin-3 in regulating BBB integrity was derived from studies in an animal model for multiple sclerosis or in human glioblastoma multiforme, were claudin-3 immunostaining was found to be specifically lost in inflamed CNS microvessels." (PMID 31671721, 2019).
melanoma (4 papers, 2017 to 2024). A malignant, usually aggressive tumor composed of atypical, neoplastic melanocytes. "This study presents evidence that loss of claudin-3 protein promotes lymphatic metastasis of B16F10 melanoma cells into draining lymph nodes accompanied with increased lymphangiogenesis." (PMID 36261482, 2022). "Our results revealed that loss of claudin-3 increased the metastasis of B16F10 melanoma cells into the draining lymph nodes in comparison with claudin-3+/+ control mice." (PMID 36261482, 2022). "Our results indicated that loss of claudin-3 in the tumor microenvironment increased melanoma lymphatic metastasis and upregulated tumor lymphangiogenesis." (PMID 36261482, 2022). "This study indicates that claudin-3 plays an important role as a signaling molecule in lymphatic endothelial cell activity associated with tumor lymphangiogenesis, which may further contribute to melanoma metastasis." (PMID 36261482, 2022). "In conclusion, this study suggests the involvement of claudin-3 processes for melanoma metastasis, and a possible mechanism is proposed." (PMID 36261482, 2022). "We are interested to explore the expression and function of claudin-3 on LECs that contribute to melanoma lymphangiogenesis." (PMID 36261482, 2022). "We found an increased lymphangiogenesis in the B16F10 tumor in claudin-3 knockout mice, accompanied by augmented melanoma cell metastasis into sentinel lymph nodes." (PMID 36261482, 2022). "In this study, we used claudin-3−/− mice to establish a popliteal lymph node metastasis model of B16F10 melanoma." (PMID 36261482, 2022). "We found that the knockout of claudin-3 in mice increased B16F10 melanoma cell metastasized into the draining lymph nodes significantly compared to control claudin-3+/+ mice." (PMID 36261482, 2022). "To study the association between claudin-3 and melanoma metastasis, we used claudin-3−/− mice and control claudin-3+/+ mice to establish a popliteal lymph node metastasis model by injecting 5 × 105 mCherry-labeled melanoma cell line B16F10 subcutaneously into the footpad." (PMID 36261482, 2022). "These novel functions of claudin-3 on LECs are worth further analysis that may provide a new target for restricting melanoma metastasis." (PMID 36261482, 2022). "CLDN3 was less common in squamous cell carcinomas (0–43.2%) and mainly absent in melanoma, mesenchymal neoplasia, and in tumors of hematopoetic and lymphoid tissues." (PMID 39658782, 2024). "CLDN3 positivity was less common in squamous cell carcinomas (0–43.2%) and mainly absent in melanoma, mesenchymal, and hematolymphatic neoplasms." (PMID 39658782, 2024). "The melanoma line Sk-Mel5 was negative for claudin-3 and -4 expression and was used as negative control in all in vitro experiments." (PMID 28193196, 2017). "The negative control human melanoma cell line SK-MEL-5 did not express Cldn3/4." (PMID 34503203, 2021).
multiple sclerosis (4 papers, 2019 to 2024). A progressive autoimmune disorder affecting the central nervous system resulting in demyelination. "In another work about claudin-3 in multiple sclerosis, authors also found a normal tight and adherence junction expression profile like beta-catenin, claudin-11 and ZO-1 at the choroid plexus in claudin-3 null mice." (PMID 36261482, 2022). "BBB damages caused by dysfunctional cellular components, such as β-catenin-mediated CLDN3 downregulation, are known to be related to the onset and progression of various neurological diseases, including stroke, multiple sclerosis, epilepsy, and Alzheimer’s disease." (PMID 38584257, 2024). "Multiple sclerosis is characterised by decreased levels of claudin-11 at the BBB of patients and of claudin-3 in a mouse model which exhibits lowered barrier tightness." (PMID 38891789, 2024). "Changes of claudin-3 at the BBB are found in experimental ischemia/reperfusion, haemorrhage, and chronic inflammatory pain in a multiple sclerosis model (experimental autoimmune encephalitis) or in human glioblastoma multiforme." (PMID 38891789, 2024). "In addition, claudin-3 may be involved in maintenance of BCSFB TJ integrity, since its absence was found to impair BCSFB integrity in a mouse model for multiple sclerosis which was however not confirmed in a second study." (PMID 31671721, 2019).
necrotizing enterocolitis (4 papers, 2014 to 2022). Necrotizing enterocolitis (NEC) is a devastating disease that affects mostly the intestine of premature infants. "In addition, urinary claudin-3 levels were significantly higher in neonates with necrotizing enterocolitis than in neonates with other diagnoses." (PMID 34778138, 2021).
ovarian serous adenocarcinoma (4 papers, 2009 to 2017). An adenocarcinoma that arises from the ovary and is characterized by the presence of malignant epithelial cells that, in well differentiated tumors, resemble the epithelium of the fallopian tube or, in poorly differentiated tumors, show anaplastic features and marked nuclear atypia. "In contrast, in another study high CLDN3 expression in ovarian serous adenocarcinoma was correlated with shorter survival in both univariate and multivariate analyses." (PMID 23805314, 2013). "Genes characteristic of ovarian serous adenocarcinoma, including a well known marker CLDN3, as well as potentially some novel markers, were identified by comparing gene expression profiles of ovarian adenocarcinoma to those of normal ovary." (PMID 19426511, 2009). "Overexpression of CLDN3 predicts poor prognosis of ovarian serous adenocarcinoma." (PMID 28160565, 2017). "We have previously performed an immunohistochemical analysis of the expression of CLDN3 and CLDN4 in the Fallopian tubes of 6 patients with serous ovarian cancer and found that both the distal Fallopian tubes and serous ovarian cancers themselves expressed these two proteins in abundance." (PMID 23805314, 2013).
squamous cell carcinoma (4 papers, 2014 to 2024). A carcinoma arising from squamous epithelial cells. "CLDN3 positivity was less frequent in squamous cell carcinomas and, as described by others, only rarely seen in hematolymphoid and in most mesenchymal neoplasms." (PMID 39658782, 2024). "However, when comparing adenocarcinoma with squamous cell carcinoma, significant differences were observed in the expression of CLDN-3, CLDN-4, and CLDN-7." (PMID 38338691, 2024). "IGF-1 has been shown to increase transepithelial electrical resistance (a measure of barrier function) by regulating occludin and claudin-3 in submandibular gland cells, zona occludens (ZO)-1 in A431 human epidermoid carcinoma cells and claudin-1 in osteoblast cells." (PMID 24618563, 2014).
Stroke (4 papers, 2014 to 2024). Sudden impairment of blood flow to a part of the brain due to occlusion or rupture of an artery to the brain. "believed that Cldn3 and occludin could not only protect tight junctions and kept the BBB intact in stroke, but also promoted edema and infarction, as they described the ambivalent effects of sealing proteins." (PMID 35338575, 2022).
triple-negative breast carcinoma (4 papers, 2019 to 2025). An invasive breast carcinoma which is negative for expression of estrogen receptor (ER), progesterone receptor (PR), and human epidermal growth factor receptor 2 (HER2). "High level of cytoplasmic claudin-3 expression in triple negative breast carcinomas has been associated with poor survival." (PMID 39687048, 2024). "Low expression of claudin-3 is an important characteristic of the triple-negative breast cancer subclass." (PMID 31614718, 2019). "Recently, claudin-3 and -7 are also considered as novel prognostic factors in triple-negative breast cancer (TNBC) through its aberrant immunohistochemical expressions." (PMID 31861759, 2019). "Claudin-3 cytoplasmic expression is an indicator of poor survival in triple-negative breast cancer." (PMID 31861759, 2019). "Genomic studies have uncovered a claudin-low subtype of triple-negative breast cancer (TNBC), characterized by reduced expression of CLDN3 (claudin 3), CLDN4 (claudin 4), CLDN7 (claudin 7), and E-cadherin." (PMID 39858010, 2025). "In triple negative breast carcinomas (TNBC) high cytoplasmic but not membranous claudin-3 and claudin-7 expression is predictive of poor outcome according to a study group, while another group has shown that membranous claudin-3 overexpression is associated with poor survival in TNBCs." (PMID 39687048, 2024).
colorectal adenocarcinoma (3 papers, 2013 to 2024). The most common type of colorectal carcinoma. "Here, we report that epidermal growth factor (EGF) increases the expression of claudin-3 in human colorectal adenocarcinoma HT-29 cells." (PMID 24069372, 2013). "Initially, we examined changes in the expression levels of claudin-1 and claudin-3 after EGF treatment in two colorectal adenocarcinoma cell lines, Caco-2 and HT-29, which differ in differentiation status and metastatic potential." (PMID 24069372, 2013). "In the present study, we show that the EGF-mediated increased expression of claudin-3 is related to increased cell migration and the formation of anchorage-dependent and anchorage-independent colonies in human colorectal adenocarcinoma HT-29 cells." (PMID 24069372, 2013). "A more recent study demonstrated nuclear localization of CLDN3 in colorectal adenocarcinoma." (PMID 33386991, 2021).
enteritis (3 papers, 2022 to 2024). Inflammation of the small intestine. "In terrestrial animals, studies on broilers showed that MOS could reduce the concentration of serum DAO and endotoxin, and maintain intestinal Occludin and Claudin-3 expression under enteritis model conditions." (PMID 35624670, 2022).
gastric adenocarcinoma (3 papers, 2021 to 2024). "The prognosis of advanced gastric adenocarcinomas can be predicted by evaluating the Claudin-3-promoter methylation status, which results in decreased protein levels." (PMID 38542354, 2024).
ischemia (3 papers, 2019 to 2025). A hypoperfusion of the BLOOD through an organ or tissue caused by a PATHOLOGIC CONSTRICTION or obstruction of its BLOOD VESSELS, or an absence of BLOOD CIRCULATION. "In this study, we utilized a rat model of intestinal ischemia–reperfusion to investigate the relationship between the dynamic changes in serum zonulin and claudin-3 and intestinal mucosal injury." (PMID 41255609, 2025).
lung squamous cell carcinoma (3 papers, 2019 to 2024). "Through Wnt/β-catenin signaling pathway inhibition, CLDN3 prevents EMT in lung squamous cell carcinoma." (PMID 36620607, 2022). "In brief, claudin-3 and -6 are correlated with lymph node metastasis in squamous cell lung carcinomas." (PMID 31861759, 2019). "CLDN3 expression is increased in lung adenocarcinoma compared with lung squamous cell carcinoma." (PMID 36620607, 2022).